PABIR2 (PABIR family member 2)
Synonyms: FAM122B; DKFZp686L20116; RP11-308B5.5; SPACIA2
Tractability: No criterion of Open Targets' tractability assessment is met for any kind of drug.
Gene: Protein-coding gene on chromosome X (134,769,566 to 134,797,232, reverse strand). Ensembl gene ENSG00000156504.
Subcellular location (Human Protein Atlas): Nucleoplasm
Gene Ontology:
Molecular function: protein serine/threonine phosphatase inhibitor activity
Biological process: positive regulation of proteasomal ubiquitin-dependent protein catabolic process
Cellular component: cytoplasm; nucleus
Homologues: Orthologues: chimpanzee PABIR2 (100% identical), macaque PABIR2 (99% identical), mouse Pabir2 (80% identical), rat Pabir2 (80% identical), dog PABIR2 (79% identical), guinea pig PABIR2 (79% identical), pig PABIR2 (78% identical), zebrafish pabir2 (64% identical), Drosophila melanogaster CG4497 (32% identical), Caenorhabditis elegans F46H5.2 (30% identical). Paralogues in human: PABIR1 (70% identical), PABIR3 (47% identical).
Diseases named in the same sentence as PABIR2 in open-access papers:
PABIR2 is named in the same sentence as 4 diseases in open-access papers, as found by Europe PMC text mining. Sharing a sentence is not in itself a finding about the gene and the disease.
PABIR2 shares sentences with these, for which no sentence is quoted: breast tumor (1 paper); infection (1); infectious disease (1); viral infection (1).